HLA-E (major histocompatibility complex, class I, E)
Diseases named in the same sentence as HLA-E in open-access papers (continued):
Sharing a sentence is not in itself a finding about the gene and the disease.
tumor (continued). "Generating NK cells that do not express NKG2A receptor was found to increase their cytotoxicity towards HLA-E-bearing tumours." (PMID 35806034, 2022). "A potential advantage of anti-HLA-E mAbs over anti-NKG2A mAbs is their ability to exploit the ADCC capability of NK cells to further enhance the elimination of tumours." (PMID 36560403, 2022). "High expression of the inhibitory receptor NKG2A on tumor-infiltrating NK cells and its ligand human leukocyte antigen E (HLA-E) on the surface of tumor cells was correlated with reduced cytotoxicity and disease progression." (PMID 35962192, 2022). "In summary, XPO1 inhibition primes cancer cells for NK cell mediated cytotoxicity via HLA-E downregulation, and SINEs in combination with NK cell directed therapies has potential to promote anti-tumour responses in patients." (PMID 36560403, 2022). "When transduced with NKG2A PEBLs, NK cells showed higher cytotoxicity against HLA-E expressing tumour cells and extended the survival of AML-bearing mice." (PMID 36560403, 2022). "In contrast to classical HLA molecules, which are commonly lost, the expression of HLA-E is generally elevated within tumor cells." (PMID 36032104, 2022). "The NK cell cytotoxic capability is lost when tumor-associated HLA-E binds to the CD94/NKG2A receptor, resulting in tumor progression and reduced survival." (PMID 35214796, 2022). "FGL2, encoding fibrinogen-like protein 2, and HLA-E, encoding MHC class I antigen E, were significantly differentially expressed in tumor tissues; however, their expression levels were comparable at different stages of ccRCC." (PMID 35127943, 2022). "In the tumor microenvironment of those primary HLA-E/β2m+ tumors, NK cells and mostly CD8+ αβ T lymphocytes preferentially expressed the inhibitory CD94/NKG2A receptor." (PMID 34211852, 2021). "It was reported that resistance mechanisms are used by tumor cells to evade immune recognition by HLA‐E upregulation." (PMID 33635003, 2021). "We have previously demonstrated that about 20% of CRC aberrantly overexpressed HLA-E/β2m by tumor cells." (PMID 34211852, 2021). "Selinexor blocks NKG2A mediated inhibitory activity via the downregulation of its ligand HLA-E on the surface of tumor cells." (PMID 34926302, 2021). "Ironically, HLA-E expression on tumor cells is induced by interferon-gamma (IFN-γ), which is produced by active immune cells." (PMID 34952595, 2021). "HPA031454 is an antibody against HLA-E, which showed lower intensity in tumor tissue than in normal tissue." (PMID 33692827, 2021). "The majority (22/26, 85%) of EwS samples expressed HLA-E on tumor cells, infiltrating macrophages or both." (PMID 34201079, 2021). "In contrast, NKG2A is an inhibitory receptor that recognizes HLA-E molecules on the tumor cells and lead to immune tolerance." (PMID 34952595, 2021). "Both HLA-G and HLA-E are commonly overexpressed on tumor cells, and expression is inducible by inflammatory cytokines." (PMID 34201079, 2021). "And the results showed that NKG2A downregulation was associated with the higher cytotoxicity of NK cell in decreasing HLA-E-expressing tumor cells." (PMID 34404901, 2021). "CD8+ tumor-infiltrating T lymphocytes with high PD-1 content are prevented from surviving in the tumor microenvironment by the interaction of enriched HLA-E and CD94/NKG2A inhibition." (PMID 33692827, 2021). "NKG2C+ NK cells were detectable past 3 months and effectively killed HLA-E expressing tumor targets despite their poor response to IL-12/IL-18 and low production of interferon-γ (IFN-γ)." (PMID 34199783, 2021). "A positive correlation between HLA-E expression in tumor cells and T cells and NKG2A + immune cells was reported, as well as a negative correlation with CD57 + immune cells." (PMID 34952595, 2021). "Tumour immune scores (IS) were generated through a combination of HLA-G, HLA-E, and classical HLA-class I tumour expression and numbers of tumour-infiltrating immune cells expressing FoxP3." (PMID 34361031, 2021).
tumor (continued). "In patient tissues, HLA-E was found to be highly expressed primarily on tumor cells in neoplastic compared to healthy tissue." (PMID 35082797, 2021). "To investigate a potential role of HLA-E in the immune defense of EwS, we stained pretherapeutic tumor biopsies from 26 patients with anti-HLA-E antibodies by immunohistochemistry." (PMID 34201079, 2021). "Inhibition of NKG2A expression in another study allowed NK cells to regain cytotoxic function against HLA-E+ tumor cells." (PMID 35082797, 2021). "In conclusion, we identify a novel anti-tumor mechanism for XPO1 inhibitors via HLA-E downregulation and resultant activation of NKG2A+ NK cells." (PMID 34926302, 2021). "The expression of HLA-E in tumor cells correlated with that in tumoral T cells, B cells, and macrophages, but not CD57 + NK cells." (PMID 34952595, 2021). "HLA-E was identified as a significant negative regulator of tumor NK cell sensitivity in combined analysis of two high-throughput screening methods." (PMID 35082797, 2021). "Clearly, there is an ongoing need to analyze and understand HLA-E restricted peptides in cells that are affected by tumor- or virus-induced alteration of the HLA class I presentation machinery." (PMID 34446788, 2021). "Among these discordant cases, the majority (6/8 cases) featured an overexpression of HLA-E/β2m by tumor cells in metastasis only, while only 2 cases were characterized by HLA-E/β2m overexpression in primary tumor." (PMID 34211852, 2021). "Upon ligation with peptide-loaded HLA-E molecules on tumor cells, NKG2A induces the downregulation of NK cell function, thereby leading to immune escape." (PMID 34952595, 2021). "Worse survival was associated with a high density of NKG2A+ tumor infiltrating NK cells and high levels of HLA-E in tumor tissues in patients with ovarian cancer, RCC, colorectal cancer, breast cancer, and lung cancer." (PMID 32714324, 2020). "The binding of CD94/NKG2A to HLA-E/peptide on tumor cells results in the inhibition of the effector-functions of NK cells and of other cytotoxic lymphocytes, thus leading to a poor prognosis in various solid cancers." (PMID 33255582, 2020). "In patients with HCC, high levels of NKG2A on tumor-infiltrating NK cells and high levels of HLA-E in intratumor tissues were observed, and poor prognosis was associated with the functional exhaustion of high NKG2A-expressing CD56dim NK cells." (PMID 32714324, 2020). "Despite the interactions between KIR and HLA-I control NK cell activation or inhibition, the activating receptors NKG2C and inhibitory NKG2A were also interacted with HLA-E on tumor cells." (PMID 32411806, 2020). "Blockade of the NKG2A – HLA-E interaction has been shown to improve NK cell mediated killing of GBM tumor cells." (PMID 33178210, 2020). "Increasing evidence indicates that interruption of the interaction between NKG2A and HLA-E can induce an effective anti-tumor immune response." (PMID 32714324, 2020). "Previous studies analyzed the HLA-G and the HLA-E expression as well as the tumor infiltrating immune cell composition in a large cohort of RCC lesions using a TMA." (PMID 32993793, 2020). "In the current study, by analyzing mRNA expression microarray data of 261 patients with diffuse gliomas, the correlations of HLA-E expression with tumor grade and histological type in diffuse glioma were identified." (PMID 32066399, 2020). "It has been reported that HLA-E is an effective suppressive factor, and its expression on tumor cells negatively correlates with patients’ overall survival." (PMID 32640575, 2020). "The interaction of NKG2A and HLA-E inhibited the anti-tumor effector function of both NK cells and some CD8+T cell subsets that upregulate NKG2A in the TME." (PMID 32714324, 2020). "Alternative tumor immune escape mechanisms include upregulation of HLA-E on the tumor cell surface and release of soluble NKG2D ligands, such as MICA and MICB." (PMID 32903482, 2020).
tumor (continued). "HLA-E expression was correlated with more aggressive tumor grade and histological type and was identified as an independent prognostic biomarker in LGG patients." (PMID 32066399, 2020). "Currently, the role of genetic variations in NKG2C and HLA-E in balancing anti-tumor immune response or disease outcome in hematological malignancies has not been investigated." (PMID 33218185, 2020). "Human leukocyte antigen E (HLA-E), a ligand overexpressed in tumor cells, can bind to inhibitory receptor NKG2A which dampens NK cell response to malignant growth." (PMID 33262947, 2020). "A significant positive correlation of HLA-E expression and tumor grade was identified, HLA-E gene was highly overexpressed in GBMs (0.286 ± 0.787), followed by AGs (0.176 ± 0.824) and LGGs (− 0.340 ± 0.802)." (PMID 32066399, 2020). "We further analyzed the expression of HLA-E, a ligand of NKG2A, in tumors and found that HLA-E was expressed on both tumor cells and immune cells in the tumors of NSCLC patients." (PMID 32010126, 2019). "Some key molecules, such as CALR, HLA-A, HLA-DRB1, PDIA3, HLA-DQB1, HLA-E, and TAP2, have been implicated in various types of cancers and emphasized their important values related to the tumor progression." (PMID 31258820, 2019). "A recent study indeed report strong correlations between HLA-E expression in tumor lesions and frequencies of NKG2A+ CD8+ T cells." (PMID 31623687, 2019). "Of note, however, MEM-E/02 stained terminal stages of adenocarcinoma and lymph node metastatic lesions intensely, either owing to increased expression of β2m-free HLA-E with tumor progression or owing to expression of other β2m-free HLA-Ia molecules." (PMID 31009335, 2019). "Validation analysis indicated that HLA-C, HLA-DPA1, HLA-E, HLA-F and HLA-G were associated with HCC prognosis of overall survival (all P ≤ 0.05, elevated 0.988 and 0.997 multiples compared to non-tumor tissues, respectively)." (PMID 31602270, 2019). "In vitro and in vivo studies revealed that the knockdown of NKG2A in NK cells using shRNA or siRNA instigates “missing-self” responses and promotes the anti-tumor activity against HLA-E expressing cancer cell lines." (PMID 31340613, 2019). "It was interesting that HLA-E expression was negatively correlated with the frequency of NKG2A+ CD8+ T cells in the tumor." (PMID 32010126, 2019). "NKG2A is overexpressed in NK cells from chronic lymphocytic leukemia patients, and blocking NKG2A with monalizumab is sufficient to restore the direct cytotoxicity of NK cells against HLA-E-expressing tumor cells." (PMID 31681269, 2019). "Obviously, there is a sustained need for the analysis and understanding of HLA-E restricted peptides in cells that are affected by tumor or virus induced impaired HLA class I presentation machinery." (PMID 30909402, 2019). "In human cancer samples, HLA-E was demonstrated widely expressed on the surfaces of several tumor types." (PMID 31623687, 2019). "Since human cancer cells can express both intact trimeric HLA and β2m-free HLA, there is a need to distinguish the different phenotypic expression of HLA-E on the surface of tumor lesions." (PMID 31009335, 2019). "These monospecific mAbs are also invaluable for the specific demonstration of HLA-E on tumor biopsies, potentially indicating those tumors most likely to respond to such therapy." (PMID 31009335, 2019). "For HLA-E, maintaining a conserved mode of interaction between NK cells and other somatic cells provides a consistent way to achieve tumor or immune surveillance." (PMID 31123763, 2019). "One study showed indirect effect of selenite on NK cells, where selenite induced posttranscriptional inhibition of HLA-E and sensitized tumor cells to CD94/NKG2A positive NK cells." (PMID 30324091, 2018).
tumor (continued). "Lirilumab (IPH2102) and monalizumab (IPH2201) are IgG4 monoclonal antibodies (mAbs) currently in clinical development that target KIR2DL1-3 and NKG2A, and antagonize the inhibition of NK cells mediated by HLA-C and HLA-E on tumor cells, respectively." (PMID 30250471, 2018). "Given the association between HLA-E overexpression and a poor prognosis in solid tumors, these studies support NKG2A blockade as a promising strategy to enhance anti-tumor immune responses." (PMID 30250471, 2018). "The heterodimer of NKG2A and CD94 can bind to HLA-E which is usually upregulated in tumor cells; therefore, the tumor cells escaped the NK by this inhibitory signal." (PMID 30255103, 2018). "The positive prognostic effect of stromal CD8+ T cells on OS was only apparent in patients with low expression of HLA-E on their tumor cells." (PMID 26658106, 2016). "Our study revealed that the expression of HLA-E by tumor cells was an independent prognostic factor for OS." (PMID 26658106, 2016). "They analyzed tumors by tissue microarray for the presence of Foxp3+ cells (Tregs) and tumor expression of HLA-E and HLA-G." (PMID 27652273, 2016). "NK cell anti-tumor activity in primary tumors can be further impeded by expression of non-classical MHC class I molecules such as human leukocyte antigen (HLA)-E and HLA-G on CRC cells." (PMID 27367680, 2016). "In contrast, in the present study, we found 30 % expression of HLA-E in the primary tumor for both groups." (PMID 27895918, 2016). "In fact, in SCC, there was significantly less HLA-E expression in the metastatic tumor cells compared to the primary tumor." (PMID 27895918, 2016). "Presence of high stromal CD8+ T cells correlated with improved OS and reached near-significance (HR 1.560, 95% CI 0.962-2.530, p=0.072) and hence was included in the multivariate analysis together with tumor stage, gender and HLA-E expression." (PMID 26658106, 2016). "In addition to tumor stage and gender, the increased expression of HLA-E was significantly associated with OS (HR 0.612, 95% CI 0.392-0.956, p= 0.031) indicating that low HLA-E expression is an independent positive prognostic factor for OS in pulmonary adenocarcinoma." (PMID 26658106, 2016). "Both univariate and multivariate analysis revealed high HLA-E expression by tumor cells as an independent predictor of poor prognosis." (PMID 26658106, 2016). "In conclusion, the beneficial effect displayed by tumor-infiltrating stromal CD8+ T cells is impeded when HLA-E is highly expressed by tumors." (PMID 26658106, 2016). "A high tumor expression of HLA-E completely abolished the prognostic effect of CD8+ T-cell infiltrate." (PMID 26658106, 2016). "At the site of the primary tumor, we observed 33 and 31 % expression of HLA-E and HLA-G, respectively." (PMID 27895918, 2016). "HLA-E and CD94/NKG2A expression has been reported in multiple tumor histologies and is associated with poor prognosis." (PMID 26697006, 2015). "Regarding HLA-E expression, the benefit of tumor infiltrating CTLs was abrogated presumably due to the inhibition of CD94+/NKG2A+ CTLs by HLA-E." (PMID 25401109, 2014). "Regarding NKG2A-mediated inhibition of NK cells by HLA-E expressing tumor cells, very few data are available." (PMID 24715892, 2014). "Loss of HLA Class I tumor expression was related to a better prognosis in CRC in most studies and HLA-E and HLA-G tumor expression has been correlated with a poor prognosis and tumor progression." (PMID 24997850, 2014). "Since most tumour infiltrating microglia/macrophages are found at the border of the ischaemic area, hypoxic stimuli enhance the expression of the HLA-E and HLA-G-immune modulatory molecule as far as it induces M2 polarization." (PMID 24093459, 2013). "Several studies have reported that HLA-E overexpression is correlated with tumour progression, exhibiting a trend toward worse survival." (PMID 22947189, 2012).
tumor (continued). "Additional studies provided evidence that HLA-E expression contributes to immune surveillance and/or immune escape of virally infected cells, stressed cells, and tumour cells." (PMID 22947189, 2012). "In view of the broad tumor tissue release of HLA-E and its up-regulation by inflammatory cytokines, sHLA-E should be studied for its involvement in immune responses against tumors." (PMID 21712991, 2011). "Studies from our group and others supported an immunosuppressive potential of this expression, through engagement of the CD94/NKG2A inhibitory NKR on cytotoxic cells (NK and CD8 TIL) by tumor cell membrane HLA-E." (PMID 21712991, 2011). "Using MEM-E/02, we recently observed that HLA-E is constitutively co-expressed with HLA-A, -B, -C molecules in a fraction of neoplastic tissues and on the surface of most cultured tumor cell lines." (PMID 22032294, 2011). "Considering that IFN-γ and IFN-α are high inducers of HLA-I molecules expression, their impact upon sHLA-E production likely reflect the increase of HLA-E expression by tumor cells." (PMID 21712991, 2011). "In view of the opposing outcomes (activation or inhibition) of the different HLA-E receptors, the preferred role (if any) of HLA-E expressed in vivo on tumor cells remains to be established." (PMID 22032294, 2011). "So, it will be interesting to determine if this mechanism is also observed with HLA-E, which would then be released into the tumor microenvironment and hereby affect the local immunological status." (PMID 21712991, 2011). "Thus, we propose a dual outcome model whereby HLA-E expression, far from being a manifestation of immune inhibition and escape, represents instead a prerequisite for active immunological scrutiny of edited HLA tumor variants on the one hand, and triggering immune responses on the other." (PMID 22032294, 2011). "We have previously shown that transfection of HLA-E down-regulates the cytolytic response of TKD/IL-2-activated NK cells against tumor cells." (PMID 21179573, 2010). "Trophoblasts and tumor cells protect themselves against the attack by the innate immune system via the expression of HLA-E." (PMID 21179573, 2010). "HLA-E and HLA-F might help tumor cells evade immunity by interacting with inhibitory receptors on NK cells." (PMID 40104502, 2025). "This heterogeneity in tumor types and stages may confound the relationship between HLA-E expression and survival outcomes, thereby limiting the ability to generalize our findings." (PMID 40066089, 2025). "Taking this evidence into consideration, it can be speculated that LGG tumours may suppress the activity of beneficial tumour-infiltrating CD56dim NK cells through the HLA-E/CD94-NKG2A signalling axis." (PMID 40361496, 2025). "Therefore, mAb monalizumab increases the cytotoxic activity of NK and T CD8+ cells by blocking the binding of NKG2A/CD94 to HLA-E, which is typically stimulated by anti-tumor activity and Interferon-gamma (IFN-γ)." (PMID 40296914, 2025). "Based on these findings, we propose that targeting cancer cell senescence or HLA-E-mediated immunosuppressive events may serve as a promising strategy to restore anti-tumor immunity within the pleural metastatic niche." (PMID 40959273, 2025). "By overexpressing HLA-E, tumor cells can suppress NK cell-mediated immune responses." (PMID 40739089, 2025). "Using multiplex immunohistochemistry (mIHC), we demonstrated that PD‐1+NKG2A+ NK cells co-localize with PD‐L1+/HLA‐E+ tumor regions, revealing a spatially organized immunosuppressive niche where inhibitory ligands and suppressed NK subsets are compartmentalized." (PMID 40877861, 2025). "Taken together, it will be interesting to determine whether selinexor-mediated inhibition of the HLA-E:NKG2A axis can promote the anti-tumour function of NKG2A+ CD8+ T cells with high tumour specificity." (PMID 40291981, 2025). "In addition, HLA‐E is likely to modulate the tumor immune microenvironment, thereby impacting the survival rates of patients with LUAD." (PMID 39623605, 2024).